IL24 (interleukin 24)
Diseases named in the same sentence as IL24 in open-access papers (continued):
Sharing a sentence is not in itself a finding about the gene and the disease.
tumor (continued). "Although IL-24 is not a classical tumor suppressor, its ability to inhibit multiple cell signaling pathways that are required for tumor growth, invasion, metastasis and angiogenesis places it in a unique class of anticancer agents." (PMID 24377906, 2013). "Subsequent studies showed receptor-positive tumor cells transduced with Ad-IL-24 or transfected with IL-24 plasmid DNA and overexpressing IL-24 when mixed with receptor-negative tumor cells resulted in killing of both receptor-positive and –negative cells." (PMID 24377906, 2013). "The inhibitory activity of IL-24 on cell migration and invasion was shown to be independent of tumor cell killing." (PMID 24377906, 2013). "The anti-tumour effect by in vivo assay, the ZD55-IL-24 is also much higher than that of Ad-IL-24." (PMID 23675261, 2012). "Despite the promise of MDA-7/IL-24 and SM7L therapy, the results of this study and multiple other studies suggest that these mono-therapies primarily slow tumor cell growth and the remaining residual tumor has the potential for rapid tumor recurrence upon termination of the therapy." (PMID 22808125, 2012). "Thus, we consider that although the cancerous characteristics of MLS cells have potential to induce MDA-7/IL-24 expression, TLS–CHOP represses it and contributes to maintain the tumour growth." (PMID 22588557, 2012). "Interestingly, while CD4+ T cell depletion in calcipotriol-treated tumors reduced IL-24+ macrophages, it had no significant impact on the total number of macrophages in the tumor." (PMID 39782693, 2025). "Activated macrophages’ release of IL-24 can inhibit tumor cell growth without harming normal cells." (PMID 39782693, 2025). "In particular, E1B55-kDa gene defective oncolytic adenoviruses (Ad-ZD55) not only efficiently infects and replicates in tumor cells, but also amplifies IL-24 gene to enhance the expression and function of IL-24 in tumor microenvironment without affecting adjacent normal cells." (PMID 33613773, 2021). "In addition, IL-24 shows special antitumor activity and can kill nearby tumor cells without toxicity to normal cells." (PMID 34685354, 2021). "The molecular/biochemical basis for this profound “bystander” anticancer effect is partly through secreted MDA-7/IL-24 protein binding to dimeric IL-20/IL-22 surface receptors inducing production of MDA-7/IL-24 protein via a paracrine-autocrine feedback loop in adjacent and distant tumor cells." (PMID 33670594, 2021). "Recent studies have suggested that adenovirus-mediated IL-24 may also potentially enhance immunosurveillance against tumor cells by increasing the levels of CD8+ T cells in mammary tumors and fibrosarcoma, thereby contributing to tumor suppression in mice." (PMID 33419310, 2020). "However, IL-24 did not influence either peripheral or tumor-infiltrating Th17 percentage in either low or high concentration manner (One-way ANOVA, P > 0.05)." (PMID 31921658, 2019). "Furthermore, low concentration of IL-24 slightly up-regulated tumor-infiltrating Treg frequency, but this difference failed to achieve statistical significance (10.01 ± 2.24% vs. 8.97 ± 2.08%, Tukey test, P = 0.098)." (PMID 31921658, 2019). "Furthermore, restoring IL-24 protein expression using viral and non-viral-based gene IL-24 delivery resulted in suppression of tumor growth, angiogenesis, and metastasis both in vitro and in vivo." (PMID 31783569, 2019). "Although simultaneous VP3, interleukin-24, interleukin-18, upregulations and survivin downregulation seemed to show greater anti-tumor activity than VP3 alone, the combined effect of VP3 and shRNA on CD147 affecting tumor growth and progression is yet to be investigated." (PMID 27411985, 2016).
tumor (continued). "In contrast, we could observe GFP-expressing cells negative for IL-24 expression among tumor tissues in the group of MSC.LentiR+Ad-hTERTp-IL24." (PMID 27322080, 2016). "It indicates that IL-24 only harmful to tumor cells and almost have no damage to normal cells." (PMID 26361755, 2015). "In summary, our study results demonstrate IL-24 disrupts the SDF-1/CXCR4 signaling pathway resulting in reduced cell migration and invasion and combination therapy of IL-24 with pharmacologic or genetic CXCR4 inhibitor produced a greater inhibitory activity on tumor cell migration." (PMID 25775124, 2015). "Additionally, IL-24 inhibited tumor cell migration both in the presence and absence of the CXCR4 agonist, SDF-1." (PMID 25775124, 2015). "Thus, mda-7/IL-24 expression appears to be shut down during tumor evolution, explaining the delayed, rather than complete, suppression of tumor formation in the doxycycline-treated mice, and the robust growth of these tumors once formed." (PMID 26460950, 2015). "Receptor-negative tumor cells did not undergo cell death when treated with IL-24 protein." (PMID 24377906, 2013). "Additionally, testing IL-24 as a gene therapeutic overcomes the limitations of vector transduction efficiency and does not require the tumor in its entirety to be transfected and express IL-24 for producing observable antitumor activity." (PMID 24377906, 2013). "Additionally, overexpression of IL-24 protein in normal cells did not elicit any cytotoxicity indicating IL-24 had selectivity towards tumor cells." (PMID 24377906, 2013). "However, knock-down of STAT-3 did not abrogate IL-24 protein-mediated killing of the receptor-positive tumor cells indicating STAT-3 activation was not required for tumor cell killing." (PMID 24377906, 2013). "Another question raised was whether the secreted IL-24 protein had any inhibitory effect on neighboring tumor cells that did not express IL-24?" (PMID 24377906, 2013). "This study also demonstrated that IL-24 protein selectively kills receptor-positive but not receptor-negative tumor cells when bound to its receptor thus providing an extracellular-protein mediated tumor cell killing." (PMID 24377906, 2013). "Treatment of cells with Ad-IL24 resulted in IL-24 protein expression that bound and inactivated HSP70 family chaperone BiP/GRP78, which in turn promoted dissociation and activation of PKR-like endoplasmic reticulum kinase (PERK) resulting in initiation of tumor cell apoptosis." (PMID 24377906, 2013). "The percent of tumor cellspositive for MMP-2 expression was significantly decreased in the INF-αgroup compared with the controls, and the MMP-2 levels in the combined therapygroup were further significantly reduced compared to the IFN-α, control,and IL-24 groups." (PMID 22569271, 2012). "In CNHK600-EGFP group, the tumor inhibition rate was 21.49%, and the tumor inhibition rates of the CNHK600-IL24 low-dose, medium-dose and high-dose groups reached 36.91%, 42.98% and 49.86%, respectively (P < 0.05, EGFP group vs. IL24 high-dose group student’s t-test)." (PMID 22640485, 2012). "Although the pathways by which MDA-7/IL-24 enhances apoptosis in tumor cells are not fully elucidated, evidence from several studies suggests that MDA-7/IL-24 mediates many proteins important for the onset of growth inhibition and involvement of the mitochondrial apoptotic cell death pathway." (PMID 22629368, 2012). "Based on the potent anti-tumor activity and receptor-targeted specificity of MDA-7/IL-24, we reasoned that a novel and highly effective multifunctional anti-cancer molecule could be created by re-engineering of wild-type MDA-7/IL-24." (PMID 22808125, 2012). "Interestingly, instead of the more commonly seen JAK/STAT signaling pathway, these tumor suppressive effects can also be mediated via activation of the p38 mitogen-activated protein kinase (MAPK) pathway, suggesting the complexity of IL-24 signaling in the regulation of cellular responses." (PMID 35054813, 2022).
tumor (continued). "The combinational treatment of Oncolyticvaccinia virus VV‐IL‐24 and luteolin resulted in stronger oncolysis and IL‐24 expression compared with VV‐IL‐24 treatment alone, which could promote HCC cell apoptosis and antiangiogenesis effect, suppress tumor cell proliferation." (PMID 33274495, 2021). "Therefore, tumor cells modified with recombinant nonlytic NDV expressing IL-24 may have superior effects of stimulating T cell responses than those with parental virus." (PMID 31338417, 2019). "Moreover, overexpression of IL‐24 in subcutaneous lung tumor xenograft models led to a reduction in CD31 expression, supporting the hypothesis that IL‐24 overexpression inhibits in vitro differentiation of endothelial cells, potentially contributing to a decrease in tumor angiogenesis." (PMID 40338095, 2025). "Re‐challenging the C3H mice with parental tumor cells also showed no tumor growth, but revealed an increased population of CD3+/CD8+ cells and elevated Th1 cytokine levels, suggesting systemic immunity resulting from IL‐24 treatment." (PMID 40338095, 2025). "They found immunocompetent mice injected with Ad.mda-7-transduced UV2237m failed to develop any tumors and when these tumor-free mice were challenged with parental tumor cells, no tumor growth was apparent, suggesting a potential vaccine effect of MDA-7/IL-24." (PMID 35008495, 2021). "The results showed that B16-LX/IL-24 could not provide any increased preventive effects against EL-4 cells, as compared with irradiated B16-immunized mice, suggesting that the antitumor response induced by LX/IL-24-modified tumor cells was specific to autologous tumor." (PMID 31338417, 2019). "In vivo studies demonstrated mice implanted with a mixture of IL-24 producing human embryonic kidney cells (HEK)-293 and human receptor-negative A549 lung tumor cells underwent tumor growth inhibition." (PMID 24377906, 2013). "In contrast, high concentration (100 ng/ml) of IL-24 stimulation promoted both CD4+ and CD8+ T cell function, which presented as increase of Th1/Th17 cells and elevation of cytolytic and non-cytolytic activity of peripheral and tumor-infiltrating CD8+ T cells." (PMID 31921658, 2019). "In contrast, we observed the combination of mNSC-SM7L/TRAIL nearly eliminated tumor burden within 5 days of treatment, induced greater GBM killing than the combination of MDA-7/IL-24 and radiation, and was observed without pre-treatment of cells prior to implantation." (PMID 22808125, 2012). "With the same IL-24 gene, Ad•DD3•E1A•(IL-24) or Ad•AFP•E1A•ΔE1B•(IL-24) could completely eliminate xenograft tumor, but the Ad•AFP•E1A•E1B(Δ55)•IL-24 could not, showing the importance of vector." (PMID 23675261, 2012). "Low concentration of IL-24 did not affect either perforin or granzyme B expression in CD8+ T cells (Tukey tests, P > 0.05), while high concentration of IL-24 promoted perforin and granzyme B expression in both peripheral and tumor-infiltrating CD8+ T cells (Tukey tests, P < 0.05)." (PMID 31921658, 2019).
cancer (153 papers, 2007 to 2026). A tumor composed of atypical neoplastic, often pleomorphic cells that invade other tissues. "IL-24 is induced by Th2-associated cytokines in cancer cells and its overexpression causes toxic autophagy in the cells." (PMID 39744942, 2025). "IL-24 exhibits dose-dependent and context-sensitive biological activity, which underlies its paradoxical roles in inflammation, immune regulation, and cancer." (PMID 40607413, 2025). "Several studies have demonstrated that IL-20, IL-22, and IL-24 are involved in the regulation of programmed cell death by apoptosis and/or autophagy, widely implicated as physiological barriers to cancer development." (PMID 40806452, 2025). "Our findings demonstrate that calcipotriol-plus–5-FU–stimulated Th2 immunity eliminates precancerous skin lesions by inducing IL-24 in premalignant keratinocytes, which causes toxic autophagy in a cancer-selective manner." (PMID 39744942, 2025). "Th2-associated cytokines induced IL-24 expression in cancer cells, resulting in toxic autophagy and anoikis followed by apoptosis." (PMID 39744942, 2025). "Interleukin 24 (IL24) has been extensively implicated in carcinogenesis, affecting various aspects of cancer development." (PMID 38456941, 2024). "Overall, studies suggest that in cancer cells, IL-24 causes ER stress, which induces the production of ROS." (PMID 37444474, 2023). "IL24 regulates many cancer-associated pathways and oncogenes, including apoptosis activation and cell cycle regulation pathways." (PMID 35984577, 2022). "Recent evidence indicates that the IL24 mRNA is an underlying candidate for gene treatment of cancer through boosting apoptosis in many types of cancer cells." (PMID 33014054, 2020). "Compared with normal cells, cancer cells have higher levels of ER stress, which makes them more susceptible to ER stress-mediated cell death triggered by IL24 mRNA." (PMID 33014054, 2020). "Interleukin-24 (IL-24), also known as melanoma differentiation associated gene-7, is a multifunction cytokine that has been studied for its specific anti-cancer properties." (PMID 30669553, 2019). "We have shown that overexpression of IL-24 is implicated in endoplasmic reticulum (ER) stress-mediated apoptosis in cancer cells." (PMID 30424508, 2018). "It is anticipated that further clarification of the molecular events associated with IL-24 will enable novel avenues for therapeutic intervention in both cancer and inflammatory diseases." (PMID 27271601, 2016). "Interleukin-24(IL-24), also referred to as melanoma differentiation-associated gene-7(mda-7), is a unique member of the IL-10 gene family, which displays nearly ubiquitous cancer-specific toxicity." (PMID 26361755, 2015). "The Mda-7, Melanoma differentiation associated gene 7/IL-24, is a secreted cytokine with selective activity against cancer, with anti-apoptotic and anti-angiogenic ability." (PMID 22666387, 2012). "While information summarized above shows a significant association between IL‐24 and T cell‐mediated immune responses in cancer, the underlying molecular mechanisms and effect of IL‐24 on other immune cell subsets such as dendritic cells macrophages, and natural killer (NK) cells are not yet clear." (PMID 40338095, 2025). "During cancer progression, there is a notable loss of IL‐24 expression in cancerous cells." (PMID 40338095, 2025). "Furthermore, information pertaining to IL‐24 gene mutations or polymorphisms contributing to cancer progression is unavailable." (PMID 40338095, 2025). "Utilizing CAR‐engineered NK cells in cancer immunotherapy holds great promise, but the molecular mechanisms underlying their antitumor phenotype and the potential impact of IL24 on CAR‐loaded iNK cells remain unclear." (PMID 38737469, 2024). "Besides IL24, other candidates AhR downstream genes both associated with cancer and migration were proposed to participate in the migration regulation of rutaecarpine by RNA-Seq and bioinformatic analysis." (PMID 34955744, 2021).
cancer (continued). "Moreover, miR-221 is downregulated by the overexpression of mda-7/IL-24 in a cancer cell-specific manner, and downregulation of miR-221 can cause toxic autophagy and cancer cell-specific death." (PMID 32477928, 2020). "In conclusion, IL24 mRNA may be used as a potential marker for cancer screening, and its clinical diagnostic value needs to be further studied." (PMID 33014054, 2020). "Here we show that IL-24 causes inhibition of eIF4A in a wide variety of cancer cells." (PMID 29786657, 2018). "Two explanations might account for the synergy: first, the expression level of CAR was increased in response to the 5-Fu treatment, causing the higher viral uptake; second, over-expressed IL-24 could enhance sensitivity of cancer cells to 5-Fu." (PMID 27322080, 2016). "We further speculated that both the pharmacokinetics and anti-cancer efficacy of the novel multifunctional MDA-7/IL-24 variant would be improved by delivery via engineered stem cells." (PMID 22808125, 2012). "Interleukin‐24 (IL‐24), a versatile cytokine, has been evaluated as a cancer therapeutic in various preclinical cancer models and clinical trials, and has yielded promising results." (PMID 40338095, 2025). "Subsequently, the ability of IL‐24 secreted from normal cells to exert biological effect on uninfected DU145 cancer cells was evaluated." (PMID 40338095, 2025). "Cancer immunotherapy is enhanced by delivering IL-24 in genetically engineered T cells, further supporting its potential as a safe anticancer cytokine." (PMID 39744942, 2025). "IL-24, a tumor suppressor cytokine, plays a dual role by directly killing cancer cells and modulating the immune microenvironment to amplify antitumor responses." (PMID 40866941, 2025). "As a result, combination therapy of IL‐24 with immune checkpoint inhibitors is considered a promising strategy to improve therapeutic outcomes in cancer." (PMID 40338095, 2025). "IL-19, IL-20, and IL-24 are expressed particularly by TH type 2 cells, which orchestrate protective type 2 immune responses and protective function in some cancers but also contribute to chronic inflammatory diseases." (PMID 40806452, 2025). "We and others have previously demonstrated that IL-24 induces apoptosis in cancer cells through two primary mechanisms: activating endoplasmic reticulum (ER) stress and causing mitochondrial dysfunction." (PMID 40072085, 2025). "Recent reports have demonstrated the immunotherapeutic potential of IL-24, with its immunomodulatory activity combined with the apoptotic and anti-angiogenic properties, strengthening its utility in cancer immunotherapy." (PMID 40661937, 2025). "The outcomes of these studies are highly encouraging and serve as evidence for the successful translation of bench to bedside concepts employed in the realm of IL‐24 as a cancer therapeutic." (PMID 40338095, 2025). "Understanding the complex regulatory functions of IL‐24 biology in other human diseases holds the promise of developing novel therapeutic strategies for managing both these conditions and cancer." (PMID 40338095, 2025). "Compelling evidence from a multitude of preclinical models (in vitro and in vivo) regarding the use of IL‐24 as an anti‐cancer therapeutic has paved its way into clinical trials." (PMID 40338095, 2025). "In this context, several studies employing various in vitro and in vivo models have demonstrated that IL‐24 treatment sensitizes cancer cells to radiation therapy." (PMID 40338095, 2025). "Adenovirus‐mediated IL‐24 overexpression induced apoptosis in cancer cells by triggering ER stress, characterized by increased p‐eIF2α, CHOP, and BiP and generation of reactive oxygen species (ROS)." (PMID 40338095, 2025). "The synergistic effects of NKG2D and IL24 underscore the potential of these exosomes as a promising therapeutic strategy for cancer immunotherapy." (PMID 40076725, 2025).